FCGBP (Fc gamma binding protein)
Diseases named in the same sentence as FCGBP in open-access papers (continued):
Sharing a sentence is not in itself a finding about the gene and the disease.
FCGBP also shares sentences with these, for which no sentence is quoted: head and neck squamous cell carcinoma (4 papers); adenocarcinoma (3); cholangiocarcinoma (3); Crohn disease (2); Parkinson disease (2); Allergy (1); benign breast tumors (1); bone tumor (1); breast carcinoma (1); cardiovascular diseases (1); chronic cholecystitis (1); ciliopathies (1); esophageal cancer (1); gastric adenocarcinoma (1); gastric neoplasm (1); head and neck cancer (1); Hepatic steatosis (1); hip fracture (1); Immunodeficiency (1); inflammation (1); Insulin resistance (1); kidney chromophobe carcinoma (1); kidney diseases (1); laryngeal squamous cell carcinoma (1); leiomyoma (1); lung adenocarcinoma (1); lung diseases (1); lymph node metastases (1); metastatic colorectal cancer (1); metastatic tumor (1).
A further 9 diseases each share a sentence with FCGBP in 1 paper.